WNT5A (Wnt family member 5A)
Diseases named in the same sentence as WNT5A in open-access papers (continued):
Sharing a sentence is not in itself a finding about the gene and the disease.
Arthritis (12 papers, 2015 to 2023). Inflammation of a joint. "Due to the association of Wnt5a with clinical arthritis, we sought to determine its role in the murine STIA model of RA." (PMID 28724439, 2017). "Wnt5a has been implicated as a possible contributor to arthritis and it is upregulated in synovial fibroblasts from RA patients." (PMID 28724439, 2017). "The analysis confirmed that not only in vitro myeloid cells, but also in vivo primary murine cells transcriptional expression of Wnt5a in arthritis associated with enrichment of active marks such as H3K36me3, and H3K27Ac, and reduced levels of H3K27me3 around the TSS region of respective genes." (PMID 34663428, 2021). "Also, the inducible Wnt5a deficiency in mice reduced the severity of arthritis in the K/BxN serum-transfer model, an effect that has been attributed to decreased inflammation and osteoclastogenesis." (PMID 33178184, 2020). "Similarly, IL-1β stimulated Wnt5a expression through activation of NF- κB and the subsequently overexpression of p65 in chondrocytes, while BAY11–7082, a specific inhibitor of IκBα-phosphorylation, abrogated the induction of Wnt5a by IL-1β in the cartilage destruction caused by arthritis." (PMID 31420042, 2019). "The previous study showed that Wnt5a increased the expression of rank and active osteoclastogenesis in a murine arthritis model." (PMID 35055107, 2022). "Together these findings for the first time revealed that SETD2 mediated epigenetic regulation of Wnt5a plays a critical role in osteoclastogenesis and induced arthritis." (PMID 34663428, 2021). "To define the role of SETD2 in the WNT5a signaling in the context of osteoclastogenesis, we exploited two different models: in vitro osteoclast differentiation, and K/BxN serum-induced arthritis model." (PMID 34663428, 2021). "We found that SETD2 and WNT5a were upregulated during osteoclast differentiation and after induction of arthritis." (PMID 34663428, 2021). "Consistent with the previous results, murine data also confirmed that H3K36me3, H3K27me3, H3K27me1, and H3K27Ac marks play significant roles in regulating Wnt5a genes during osteoclastic differentiation and arthritis development." (PMID 34663428, 2021). "These examples and the reduced severity of arthritis in the Wnt5a cKO mice support the relevance of the WNT5A modulation." (PMID 33178184, 2020). "In the process of arthritis cartilage destruction, IL-1β can upregulate the expression of Wnt5a which can upregulate the expression of matrix metalloproteinase through the mediation of JNK signaling pathway." (PMID 32299482, 2020). "The Wnt5a–Ror2 signalling pathway regulates the activity of chondrocytes, osteoblasts and osteoclasts and is overexpressed in arthritis tissues." (PMID 31313518, 2019). "Following STIA induction of RA, there was attenuated development of arthritis in the Wnt5a cKO mice in terms of ankle thickness, which plateaued below the thickness developed in the littermate controls and resolved in a similar timeframe." (PMID 28724439, 2017). "Tamoxifen-inducible, Wnt5a knockout (Wnt5a cKO) mice and littermate controls were monitored for arthritis development and joint pathology using the K/BxN serum transfer-induced arthritis (STIA) model." (PMID 28724439, 2017). "In apparent contrast to clinical arthritis, Wnt5a transcript levels were reduced at d7 after RA induction." (PMID 28724439, 2017). "This inducible ablation model also permits the ablation of Wnt5a proximal to the induction of arthritis, thereby eliminating the confounding effects of Wnt5a in bone development." (PMID 28724439, 2017). "In the present study, we used inducible Wnt5a knockout (Wnt5a cKO) and littermate control mice in the K/BxN serum transfer-induced arthritis (STIA) model." (PMID 28724439, 2017). "Wnt5a cKO mice were resistant to arthritis development compared to control littermates as assessed by ankle thickness and histologic measurements." (PMID 28724439, 2017).
Arthritis (continued). "For example, non-canonical WNT expression is increased during infection and inflammation: WNT5A is upregulated in arthritis synovial tissue, atherosclerotic plaques, psoriatic or wounded skin, and in inflammatory bowel disease." (PMID 26652024, 2015). "M10 ameliorated arthritis in the CAIA model, and inhibited RANKL, WNT5A, and Bcl-2 expression in RA FLS by blocking IL-6 signaling, likely via Janus kinase–STAT3 pathway downregulation." (PMID 29755657, 2018). "M10 inhibited RANKL and WNT5A expression in RA synoviocytes both in vivo and in vitro by downregulating the JAK-STAT3 pathway; at the same time, it ameliorated the arthritis in the CAIA mouse model in vivo." (PMID 29755657, 2018). "We present our findings on RANKL and WNT5A function in osteoclastogenesis and study the effect of the anti-gp130 antibody on RANKL and WNT5A in IL-6–stimulated RA FLS in vitro and in a collagen antibody–induced arthritis (CAIA) mouse model." (PMID 29755657, 2018). "There are no other sources of information on the MMP2 regulation by WNT5A in arthritis, but in cancer cells the two types of results can be found." (PMID 33178184, 2020). "Interestingly, it has been demonstrated that the WNT5A gene has a binding site for STAT3, and that its expression is regulated by this transcription factor, playing a very important role in the maintenance of a chronic inflammation state, as well as in the destruction of cartilage in arthritis." (PMID 29584756, 2018).
endothelial dysfunction (12 papers, 2017 to 2025). In vascular diseases, endothelial dysfunction is a systemic pathological state of the endothelium (the inner lining of blood vessels) and can be broadly defined as an imbalance between vasodilating and vasoconstricting substances produced by (or acting on) the endothelium. "In preclinical research, WNT-5a may sustain an inflammatory response and cause endothelial dysfunction." (PMID 36440011, 2022). "SFRP5 has also been shown to exhibit vascular protection, restoring Wnt5a-induced endothelial dysfunction and vascular relaxation in human vascular endothelial cells." (PMID 37504530, 2023). "Intriguingly, it has also been documented that WNT5A can promote endothelial dysfunction via the Wnt co-receptor Ryk, an atypical receptor kinase that lacks kinase activity." (PMID 36846872, 2023). "To understand the function of Wnt5a in FSAP related endothelial dysfunction, we used DKK, a Wnt5a inhibitor and siRNA to downregulate Wnt5a expression." (PMID 34992208, 2022). "The contribution of Wnt5a to endothelial dysfunction and immunity reaction has been highlighted recently." (PMID 33081636, 2020). "Recent data show Wnt5a signalling also positively correlates with triglyceride levels, vascular insulin resistance and endothelial dysfunction." (PMID 33081636, 2020). "This might be partially mediated by inhibition of pro-inflammatory effects of the Wnt5a/JNK signaling in macrophages which also plays an important role in adipose tissue inflammation and endothelial dysfunction and thus underlines the protective role of Sfrp5 on cardiovascular diseases." (PMID 28851362, 2017). "Inhibition of Wnt5a and JNK restores eNOS activation and EC function, suggesting the detrimental role of Wnt5a/JNK pathway in endothelial dysfunction during diabetic conditions." (PMID 41300494, 2025). "Silencing of RYK reversed the Wnt5a-induced endothelial hyperpermeability, and thus revealed the role of Wnt5a/RYK signaling in endothelial dysfunction." (PMID 38397878, 2024). "Wingless-type family member 5 (WNT5A), myeloid zinc finger 1 (MZF1), and lysine methyltransferase 8 (SETD8) have also been reported to elevate inflammatory factor levels and activate the nuclear factor kappa B (NF-κB) pathway to induce endothelial dysfunction." (PMID 35350980, 2022). "Notably, inhibition of Wnt5a largely reversed the protective effects from HMW-HA treatment, implying that FSAP might aggravate endothelial dysfunction and neurological deficits by regulating Wnt5a signaling." (PMID 34992208, 2022).
metastatic disease (12 papers, 2007 to 2026). "Our results suggest that ERRα-mediated WNT5A is associated with advanced PCa metastatic disease in bone, but to fully understand the molecular mechanisms and determine direct versus indirect regulation by ERRα in tumor cells, additional studies are required." (PMID 27776343, 2016). "Median expression (transcripts per million) of WNT5A pathway genes of interest based on clinical demographics, including age, gender, upper versus lower tract UC, and primary versus metastatic disease." (PMID 38558536, 2024). "Our study identified methylation changes in WNT5A between primary and metastatic tumours, and these were shared among individuals." (PMID 39164966, 2024). "Decreased methylation observed post‐AzaC treatment was also associated with restored WNT5A expression in 22Rv1 cells, further indicating that DNA methylation may have a functional role in regulating WNT5A gene expression during PrCa progression to metastatic disease." (PMID 39164966, 2024). "Peritoneal mesothelial cells and visceral adipose secrete Wnt5A, and conditional knockout of WNT5A in mesothelial cells, significantly reduced the peritoneal metastatic tumor burden." (PMID 35053353, 2022). "In summary, wnt3a and wnt5a expression is high in primary and metastatic tumors in CRC with a high concordance rate." (PMID 24564183, 2014). "WNT5A and WNT5B are ligands for and bound by FZD2 and FZD4, and this binding has been shown to drive EMT and is elevated in metastatic tumors." (PMID 26572553, 2015).
thyroid cancer (12 papers, 2009 to 2024). "In thyroid cancer, Wnt5a downregulated c-myc, which in turn is a well-established proto-oncogene activating the Wnt/β-catenin pathway." (PMID 39123414, 2024). "For instance, WNT5A suppresses cell growth and invasion in colon and thyroid cancer." (PMID 37173306, 2023). "The increased Wnt5a level inhibits cell growth and migration in thyroid carcinoma." (PMID 34108990, 2021). "Therefore, Wnt5a serves as an antagonist to the canonical Wnt signaling pathway, exhibiting tumor suppressor activity in differentiated thyroid carcinomas." (PMID 24944588, 2014). "MIR31HG may promote cell growth and migration in lung, oral, or thyroid cancer cells, via the C/EBP/Wnt5A or MAP-kinase signaling pathways, depending on the specific cell types." (PMID 36980216, 2023).
colitis (11 papers, 2015 to 2022). Inflammation of the colon. "Given that LPS induces Wnt5a expression in bone marrow cells and macrophages and that Wnt5a alters DC responses to LPS10, 11, 24, we first speculated that the inhibition of DSS-induced colitis might be caused by the loss of Wnt5a in hematopoietic cells." (PMID 26030277, 2015). "For example, in a model of DSS-induced colitis, tamoxifen-induced conditional knockout of Wnt5a resulted in reduced expression of IL-12 and IFN-γ in the colon." (PMID 29616022, 2018). "In light of the actions of Wnt-5a peptide, we examined its biological actions in the context of experimental colitis induced by dextran sulfate sodium (DSS)." (PMID 27561676, 2016). "Here we use dextran sodium sulfate (DSS)-induced colitis in mice as a model for inflammatory diseases and show that disease symptoms were milder in Wnt5a and Ror2 conditional knockout mice than control mice." (PMID 26030277, 2015). "Our results support that the Wnt5a-Ror2 axis promotes DSS-induced colitis by enhancing pro-inflammatory cytokine production in the colon." (PMID 26030277, 2015). "In the same way, studies reporting the positive effects of dietary resveratrol on Wnt pathway members in DSS-induced colitis, restoring Wnt signaling in rat colon and downregulating the protein expression of WNT5A both in spleen and colon of mice model were reported." (PMID 33806347, 2021). "Additionally, it has been reported that Wnt5a can promote interferon-γ signaling, leading to IL-12 expression in dendritic cells, thereby inducing Th1 differentiation in colitis." (PMID 32934961, 2020). "Removing Wnt5a or Ror2 in adult mice suppressed dextran sodium sulfate (DSS)-induced colitis." (PMID 26030277, 2015). "However, DSS treatment reduced Ror2 mRNA expression in B and γδT cells, suggesting that these cells are hard to respond to Wnt5a in DSS-induced colitis." (PMID 26030277, 2015). "Thus, iNOS and Wnt5a gene expression in the mice with colitis with SD decreased significantly compared with the colitis group, and their expression levels increased in the mice with colitis with SD treated with melatonin." (PMID 25625560, 2015). "Taken together, these results suggest that Wnt5a promotes IFN-γ signaling, leading to IL-12 expression in DCs, and thereby inducing Th1 differentiation in colitis." (PMID 26030277, 2015). "Taken together, these results suggested that Wnt5a secreted from cells other than hematopoietic cells, probably fibroblasts, affects DSS-induced colitis." (PMID 26030277, 2015). "Non-canonical WNT pathway elements represented by FZD5, WNT5A and NFATc1 were remarkably elevated in colitis IELs." (PMID 26652024, 2015). "Thus, the Wnt5a, if any, released from hematopoietic and intestinal epithelial cells could not be involved in colitis, and Wnt5a produced in other cells may play roles in colitis." (PMID 26030277, 2015). "Recently, we investigated the nuclear factor of activated T cell (NFAT), a downstream molecule of the noncanonical Wnt signaling expression including Wnt5a and Wnt11 in a dextran sulfate sodium (DSS)-induced colitis (DIC) model, suggesting a potential proinflammatory role in the pathogenesis of IBD." (PMID 36144473, 2022).
type 2 diabetes mellitus (11 papers, 2012 to 2024). A type of diabetes mellitus that is characterized by insulin resistance or desensitization and increased blood glucose levels. "Previous studies have found that wnt5a promotes β-cell insulin secretion and reduced concentrations in patients with type 2 diabetes." (PMID 37255814, 2023). "In summary, we found that the Wnt5a protein are involved in the pathological process of type 2 diabetes." (PMID 37255814, 2023). "Metformin can increase the level of serum Wnt5a protein in patients with type 2 diabetes in addition to improving blood glucose (Unpublished)." (PMID 37255814, 2023). "Our previous studies have confirmed that the level of Wnt5a is significantly reduced in patients with newly-onset type 2 diabetes." (PMID 37255814, 2023). "Our study found that the serum Wnt5a protein level of newly diagnosed type 2 diabetes patients was significantly increased after the intervention of the GLP-1RA compared with before treatment, and the Sfrp5 was lower than that of the control group." (PMID 37255814, 2023). "High secretion of WNT-5a is usually observed in obese individuals where it prevents differentiation of pre-adipocytes (adipogenesis) leading to type 2 diabetes." (PMID 32195204, 2019). "Therefore, this study aimed to evaluate the effect of GLP-1 RA on wnt5a levels in patients with type 2 diabetes." (PMID 37255814, 2023). "Our results confirmed that GLP-1RA may improve HOMA-β in patients with type 2 diabetes by affecting the level of Wnt5a protein." (PMID 37255814, 2023). "Our study found that the serum Wnt5a protein level of newly diagnosed type 2 diabetes patients was significantly increased after the intervention of the glucagon-like peptide-1 receptor agonist compared with before treatment, and the antagonist Sfrp5 was lower than that of the control group." (PMID 37255814, 2023). "Our previous studies also confirmed that the level of Wnt5a in patients with type 2 diabetes was significantly reduced in patients with newly-onset type 2 diabetes, and that Metformin treatment can increase the level of serum Wnt5a protein in newly diagnosed patients with type 2 diabetes." (PMID 37255814, 2023). "Our results confirm that Wnt5a protein is closely related to pancreatic islet dysfunction in type 2 diabetes, and it may be a key protein for GLP-1RA to promote insulin secretion in beta cells." (PMID 37255814, 2023). "Similarly, patients with diabetes mellitus type II have been shown to exhibit increased expression of sFRP5, a Wnt inhibitor, which has been correlated with a decrease in Wnt5a levels." (PMID 27688915, 2016). "Other ligands such as Wnt5A are reported to be low at the onset of type 2 diabetes mellitus (T2DM), but increase overtime and contribute to chronic low-grade inflammation." (PMID 38671406, 2024). "To investigate our hypothesis, we treated newly diagnosed type 2 diabetes patients with GLP-1RA for 3 months to explore the relationship between GLP-1RA, Wnt5a protein, and HOMA-β." (PMID 37255814, 2023). "It has been reported decreased in a variety of inflammatory disorders such as obesity, type 2 diabetes mellitus (T2DM) and coronary heart disease (CHD) in multiple researches as an endogenous inhibitor of WNT5A signalling pathways." (PMID 34284806, 2021).